MIR127 (microRNA 127)
Synonyms: hsa-mir-127; MIRN127; miRNA127; mir-127
Gene: MicroRNA gene on chromosome 14 (100,882,979 to 100,883,075, forward strand). Ensembl gene ENSG00000207608.
Gene Ontology:
Biological process: miRNA-mediated post-transcriptional gene silencing
Cellular component: RISC complex
Homologues: Orthologues: chimpanzee ptr-mir-127 (100% identical), macaque mml-mir-127 (99% identical), rabbit MIR127 (99% identical), rat Mir127 (99% identical), pig MIR127 (84% identical), guinea pig MIR127 (72% identical), mouse Mir127 (72% identical).